ACE (angiotensin I converting enzyme)
Diseases named in the same sentence as ACE in open-access papers (continued):
Sharing a sentence is not in itself a finding about the gene and the disease.
abdominal aortic aneurysm (5 papers, 2014 to 2025). Enlargement and ballooning of the vessel that supplies arterial blood to the abdomen, pelvis and legs. "Abdominal aortic aneurysms (AAA) are characterized by a broad, non-specific inflammatory response, and thus provide a clinical platform to evaluate the anti-inflammatory potential of ACE inhibitors." (PMID 25474105, 2014).
age (5 papers, 2021 to 2026). A temporal measurement of the time period elapsed since an identifiable point in the life cycle of an organism. "Attempts have been made to improve skeletal muscle function and delay age-related muscle atrophy by pharmacological antagonism of the ACE-Ang II-AT1R pathways using AT1R antagonists or ACE inhibitors (ACEIs)." (PMID 34548056, 2021). "This disbalance between detrimental ACE-Ang-II-AT1R axis and beneficial ACE-Ang-II-AT2R and ACE2-Ang- 1–7-MasR axes contributes to age-related cardiovascular pathologies [1016, 1023]." (PMID 40407975, 2025).
Airway obstruction (5 papers, 2018 to 2025). Obstruction of conducting airways of the lung. "Angioedema associated with ACE inhibitors has been well-documented in the literature and is recognized as a significant clinical concern, particularly due to its potential to cause life-threatening airway obstruction if left untreated." (PMID 40636633, 2025).
alcohol dependence (5 papers, 2013 to 2025). Physical and psychological dependence on alcohol. "We assessed changes in protein expression in brain regions associated with alcohol dependence, focusing on the MOR, NMDA receptor, protein phosphatase DARPP‐32 and angiotensin‐converting enzyme (ACE)." (PMID 40910474, 2025). "Some of the pathways identified in this study even suggest avenues for pharmacotherapy of alcoholism with existing agents, such as angiotensin-converting enzyme (ACE) inhibitors." (PMID 25505662, 2013).
Aortic dissection (5 papers, 2021 to 2025). Aortic dissection refers to a tear in the intimal layer of the aorta causing a separation between the intima and the medial layers of the aorta. "Two infants remained stable for years on beta-blocker or angiotensin-converting enzyme (ACE) inhibitor therapy, two required early aortic root surgery, and one died from aortic dissection following an urgent replacement of the aortic valve." (PMID 36138598, 2022).
autonomic dysfunction (5 papers, 2017 to 2026). "The Steno-2 trial reported that a multifactorial cardiovascular risk intervention (including ACE inhibition) appeared to reduce the prevalence of autonomic dysfunction by 63%." (PMID 28373993, 2017). "Angiotensin-converting enzyme (ACE) inhibitors have been shown to have some therapeutic potential to treat cardiovascular autonomic dysfunction in T2DM patients." (PMID 39596529, 2024). "Our group proposed for the first time the management of DCAN with ACE inhibitors and reported an increase in indices of 24 h HRV, which have been considered as the earliest markers of autonomic dysfunction." (PMID 28373993, 2017).
Cachexia (5 papers, 2005 to 2024). Severe weight loss, wasting of muscle, loss of appetite, and general debility related to a chronic disease. "The highly lipophilic ACE inhibitor imidapril (VitorTM) (30 mg kg−1) attenuated the development of weight loss in mice bearing the MAC16 tumour, suggesting that Ang II may play a role in the development of cachexia in this model." (PMID 16052213, 2005).
cardiac amyloidosis (5 papers, 2012 to 2024). Cardiac amyloidosis is a condition whereby cardiac tissue is infiltrated by amyloid fibrils. "The other treatments complied with the guidelines (no beta blockers, low doses of ACE inhibitors, and ARBs) applied in the French Referral Center for Cardiac Amyloidosis." (PMID 34362197, 2021).
cardiac sarcoidosis (5 papers, 2021 to 2025). Sarcoidosis affecting the tissues of the heart. "It is important to note that, although ACE and sIL-2R are included in the Japanese Circulation Society (JCS) 2016 guidelines as supportive criteria for the clinical diagnosis of cardiac sarcoidosis, their diagnostic performance is limited." (PMID 41375765, 2025).
carotid atherosclerosis (5 papers, 2014 to 2025). A thickening and loss of elasticity of the walls of carotid arteries that occur with formation of atherosclerotic plaques. "Another clinical trial demonstrated that the ACE DD genotype increases the risk of carotid artery atherosclerosis only; however, the ACE I/D genotype increases the risk of MI, HCM, LVH as well as carotid atherosclerosis." (PMID 33907634, 2021).
chronic lung disease (5 papers, 2004 to 2025). According to the definitions of the American and British Thoracic Societies, including pulmonary functional tests, X-rays, and CT scans for items such as fibrosis, bronchiectasis, bullae, emphysema, nodular or lymphomatous abnormalities. "Because of the relationship between inflammation and activation of the RAS and the association with lung fibrosis and adverse outcome in ARDS, the ACE l/D polymorphism may modify risk for the development of chronic lung disease or death in mechanically ventilated VLBW infants." (PMID 15610555, 2004). "Thus it may be relevant to examine the contribution of the ACE I/D polymorphism to chronic lung disease in a larger cohort of Caucasian infants." (PMID 15610555, 2004). "A role for genetic variation in ACE activity in both acute and chronic lung disease has recently been suggested." (PMID 15610555, 2004). "The numbers of Caucasian infants in this study are few and an effect of the ACE I/D polymorphism on the incidence of chronic lung disease or other outcomes may not be detected." (PMID 15610555, 2004).
coronary artery calcification (5 papers, 2014 to 2025). Calcification of the coronary artery, used as a measure of coronary atherosclerosis, a risk factor for myocardial infarction. "In contrast, in the cohort of non-coronary artery calcification ACE inhibitors were prescribed significantly more often than in another group." (PMID 40869134, 2025). "Our findings suggest that ACE inhibitors may help suppress the formation of coronary artery calcification (CAC) and potentially reduce cardiovascular events following PCI for calcified lesions." (PMID 40510524, 2025).
endocarditis (5 papers, 2009 to 2024). Inflammation of the endocardium. "For ACE KO, WT and NeuACE mice (ACE low, normal, high), the percentage of mice developing endocarditis was 100% (KO), 40% (WT), and 10% (NeuACE)." (PMID 38763333, 2024). "Important hemodynamic valvular dysfunction can be managed with conservative treatment (including ACE inhibitors, beta blockers, diuretics, immunosuppression, anticoagulation, and endocarditis prophylaxis) in some patients." (PMID 25401131, 2014). "In our case, we only saw indications for treatment with ACE inhibitors, prophylaxis of endocarditis, and annual follow-up." (PMID 20062791, 2009).
endometriosis (5 papers, 2019 to 2025). The growth of functional endometrial tissue in anatomic sites outside the uterine body. "A rigorous meta-analysis examined the link between endometriosis risk and genetic variations in the ACE and PAI-1 genes through eleven studies consisting of 1486 cases and 1598 controls." (PMID 40725782, 2025). "Studies on endometriosis and ACE gene polymorphism suggest that ACE gene polymorphism has some connection with the susceptibility and development of endometriosis." (PMID 36619582, 2022). "The polymorphism of the ACE c.2350A > G and ACE c.240A > T genes may be associated with the development of endometriosis." (PMID 39062484, 2024). "Endometriosis involves pathological processes including angiogenesis and fibrosis, where RAS takes part through regulatory means, with ACE serving as an essential component." (PMID 40725782, 2025). "Existing studies have indicated that ACE, HPSE, HYAL2, LMAN2, and SULF2 are related to endometriosis." (PMID 39062484, 2024). "The engagement of ACE inhibitors and ARBs in the angiotensin pathway indicates potential for these drugs to serve as non-hormonal treatment alternatives for endometriosis management." (PMID 40725782, 2025).
Glucose intolerance (5 papers, 2016 to 2019). Glucose intolerance (GI) can be defined as dysglycemia that comprises both prediabetes and diabetes. "This increased adiposity and glucose intolerance is abrogated via ACE inhibition, suggesting Ang II-mediated effects." (PMID 31262355, 2019).
hepatitis C (5 papers, 2019 to 2025). "This concept is supported by retrospectives studies reporting a possible improvement of fibrosis by ACE inhibitors in patients with hepatitis C and patients with NASH without major safety issues." (PMID 35801591, 2022).
keloid (5 papers, 2013 to 2025). An irregularly shaped, elevated mark on the skin caused by deposits of excessive amounts of collagen during wound healing. "In one study, patients with hypertrophic scars and keloids were treated with AngII receptor antagonist and ACE inhibitors and they were effective to inhibit them." (PMID 31333451, 2019). "Thus, ACE inhibition may reduce a risk factor of keloid deterioration." (PMID 23837108, 2013).
leprosy (5 papers, 2013 to 2022). Leprosy is a chronic infectious disease affecting primarily the skin and peripheral nervous system. "Indeed, the US Food and Drug Administration (FDA) approved clofazimine—an anti-leprosy drug to block the fusion event of viral spike glycoprotein and host ACE and viral helicase." (PMID 36559147, 2022).
leukocytosis (5 papers, 2012 to 2025). "Laboratory testing revealed leukocytosis with a left shift, elevated C-reactive protein (CRP), and mild increases in lactate dehydrogenase (LDH) and creatine phosphokinase (CPK), while angiotensin-converting enzyme (ACE) and soluble interleukin-2 receptor (sIL-2R) levels were within normal limits." (PMID 41170255, 2025).
leukopenia (5 papers, 2013 to 2025). "ACE inhibitors induce leukopenia in humans and mice, and the leukocyte population is the most abundant source of CD26+ cells in peripheral blood." (PMID 23734079, 2013).
male infertility (5 papers, 2016 to 2024). The inability of the male to effect fertilization of an ovum after a specified period of unprotected intercourse. "Four recessive (TRIOBP, SLC26A4, GJB2, COL4A3) and one dominant (SOX10) for the deafness; six recessive genes (LRGUK, DNAH9, ARMC4, DNAH2, RSPH6A, and ACE) for male infertility can be conclusively ascribed." (PMID 38884051, 2024). "Zinc deficiency impairs angiotensin converting enzyme (ACE) function, resulting in low testosterone levels, poor sperm quality, and a greater rate of male infertility." (PMID 36171898, 2022). "Most SNP-populated genes related to male infertility include HLA-DQB1 (20 SNPs), HLA-DRB1 (15 SNPs), MTHFR (10 SNPs), BRCA2 (9 SNPs), ACE (8 SNPs), CFTR (6 SNPs), CDH1 (6 SNPs), SRD5A2 (6 SNPs), HLA-DQA1 (5 SNPs) and MMP9 (5 SNPs)." (PMID 29263816, 2016).
metastatic disease (5 papers, 2017 to 2023). "Even in distantly metastatic disease ACE-inhibitors associated with decreased mortality (HR 0.83, 95% CI 0.76–0.91)." (PMID 34921656, 2022). "Future perspectives will involve tumor-targeted fluorescence imaging by using a fluorescent dye coupled with a specific antibody targeting a tumoral antigen (e.g., ACE) in order to identify the tumor limits and the metastatic disease along the lymph node basin." (PMID 32987841, 2020). "Thus, lower ACE activity was observed in serum from patients with high grades (G1/G2 717.38 ± 187.94 vs G3/G4 634,5 ± 192,592; Mann-U p = 0.029) and metastatic CCRCC (local disease 706,1 ± 192,81 vs metastatic disease 565.18 ± 147.05; Mann-U p = 0.009)." (PMID 28809959, 2017).
myositis (5 papers, 2014 to 2025). "The study shows that the local injections with NEP and ACE inhibitors provoked the myositis/muscle derangement processes that occur in response to the overuse." (PMID 24725470, 2014). "A pronounced inflammation (myositis) and changes in the muscle fiber morphology, including muscle fiber necrosis, occurred in the overused muscles of animals given NEP and ACE inhibitors." (PMID 24725470, 2014).
Osteopenia (5 papers, 2022 to 2025). Osteopenia is a term to define bone density that is not normal but also not as low as osteoporosis. "The overactivation of the classical arm of RAS, i.e., ACE/Ang II/AT1R, is known to stimulate the pro-inflammatory cytokines, exacerbate angiogenesis, and promote osteopenia, thus leading to the gradual destruction of the joints and increased deformation and dysfunction." (PMID 36015308, 2022).
periodontal disease (5 papers, 2021 to 2024). "ACE inhibitor use including benazepril, enalapril, lisinopril, quinapril and ramipril with respect to periodontal disease status was also analyzed in the present investigation." (PMID 37888091, 2023).
renal carcinoma (5 papers, 2000 to 2017). A carcinoma arising from the epithelium of the renal parenchyma or the renal pelvis. "NEP/CD10, ACE2 and APA expression was studied in renal carcinoma cells while ACE expression was in intratumor blood vessels." (PMID 28809959, 2017). "We recently showed an important neoexpression of endothelial angiotensin-converting enzyme (ACE) in renal cancer, what suggests a higher synthesis of tumour vessel ang II, a vasoactive hormone whose local long-term actions are related to angiogenesis in proliferative disorders." (PMID 24885240, 2014). "Captopril, an angiotensin-converting enzyme (ACE) inhibitor, has both antiangiogenic and antitumour activity in rodent models and inhibits the growth of human renal carcinoma xenografts." (PMID 15162145, 2004).
renal hypertension (5 papers, 2018 to 2022). Hypertension caused by the kidney's hormonal response to narrowing or occlusion of the renal arteries. "Our results of RT-PCR indicated that ACE is overexpressed in the hippocampus of rats with renal hypertension." (PMID 35528844, 2022). "In another study, rats with experimental renal hypertension were divided into groups and administered angiotensin converting enzyme inhibitor (ACE inhibitor) or flax lignan concentrate." (PMID 36234762, 2022). "In a recent study, AA attenuated renal hypertension by a multimodal mechanism including ACE inhibition to inhibit the AngII-AT1R and NADPH oxidase-NF-κB pathway." (PMID 30233358, 2018). "Compared with other antihypertensive agents, angiotensin-converting enzyme (ACE) inhibitors and angiotensin receptor blockers (ARBs) have the largest evidence base for efficacy and safety in paediatric patients and in patients with renal hypertension." (PMID 31118499, 2019).
steatosis (5 papers, 2015 to 2022). Increased lipid within the cytoplasm of cells. "In the present study, histological findings and hepatic lipid profiles revealed macrovesicular steatosis in liver tissues, which were reduced significantly with ACE treatment." (PMID 26508977, 2015).
sudden cardiac death (5 papers, 2014 to 2025). "Kininogen 1 is important in ACE-related pathways, and variations in KNG1 correlate with decreased risk of sudden cardiac arrest." (PMID 36312243, 2022). "Indeed, major randomized clinical trials suggest that suboptimal use of fundamental drugs, such as ACE inhibitors (ACE-i) and beta-blockers, may affect ICD shock-free survival, sudden cardiac death (SCD), and overall mortality." (PMID 24653841, 2014).
uremia (5 papers, 2009 to 2023). A clinical syndrome associated with the retention of renal waste products or uremic toxins in the blood. "Moderate uremia causes thickening of the aortic valves in apoE-/- mice, which can be attenuated by ACE inhibition." (PMID 19257900, 2009). "Moreover, to learn whether Ang II-dependent pathways may contribute to uremia-associated aortic valve thickening, we tested the effect of enalapril, an ACE inhibitor, on valvular thickening in this particular mouse model." (PMID 19257900, 2009). "The kinetic and conformational aspects of ACE phenotyping allowed identification of patients with conformationally changed ACE in the blood of patients with uremia (and in a small part of the blood samples from healthy donors)." (PMID 36831070, 2023). "Taken together, these data demonstrate that uremia induced expression of monocytic-ACE mediates the development of highly pro-atherogenic cells via an AngII-dependent mechanism." (PMID 25003524, 2014). "In summary we demonstrate uremia-induced elevation of ACE expression paralleled by a pro-atherogenic nature of ACE-overexpressing monocytes, partially mediated by enhancement of migratory and adhesion potential to endothelial monolayers." (PMID 25003524, 2014). "Uremia is characterized by an elevated level of toxic compounds and therefore served as a disorder of interest for assessing blood ACE conformation." (PMID 23166630, 2012). "Less dramatic, but still significant increase in blood ACE activity was reported in patients with renal diseases and at uremia." (PMID 23166630, 2012). "After 36 weeks of uremia, we examined the effect of ACE inhibition on maximal valve thickness in the 5/6 NX apoE-/- mice." (PMID 19257900, 2009). "The present study demonstrates a novel mouse model of aortic valve thickening, the uremic apoE-/- mouse, and reveals a potential treatment of uremia-induced valvular pathology by an ACE inhibitor." (PMID 19257900, 2009). "Such a potential of ACE was previously reported in animal and cell culture models but was not directly correlated with influences of uremia on human monocytes in vitro." (PMID 25003524, 2014). "This suggests that ACE induction is an important but most likely not the only mechanism by which uremia enhances monocyte endothelium interactions." (PMID 25003524, 2014). "Some patients with uremia due to ESRD exhibited significantly increased mAb 1G12 binding to blood ACE and increased ACE activity towards angiotensin I accompanied by reduced ACE inhibition by inhibitory mAbs and ACE inhibitors." (PMID 23166630, 2012).
Anosmia (4 papers, 2013 to 2022). An inability to perceive odors. "In addition, anosmia and dysgeusia also present in cases of head trauma and as rare side effects of common medications such as angiotensin-converting enzyme (ACE) inhibitors, angiotensin receptor blockers, dihydropyridine calcium channel blockers, diuretics, and intranasal zinc." (PMID 33041842, 2020). "In the univariate analysis, the clinical variables that had the highest positive likelihood ratios were anosmia or dysgeusia, fever, history of close contact, use of angiotensin-converting enzyme (ACE) inhibitors, lack of dyspnea, oxygen saturation below 95% on room air, and an abnormal chest CXR." (PMID 34125032, 2021).
aortic aneurysm (4 papers, 2015 to 2024). A ruptured aneurysm located in the wall of the proximal portion of the descending aorta proceeding from the arch of the aorta. "Moreover, in patients with aortic aneurysms, another cardiovascular disease where fibrosis is crucial, treatment with ACE inhibitors increased the levels of circulating type III procollagen peptide (PIIINP), suggesting active synthesis of COL385." (PMID 39301014, 2024).